RETN (resistin)
Diseases named in the same sentence as RETN in open-access papers (continued):
Sharing a sentence is not in itself a finding about the gene and the disease.
Insulin resistance (continued). "Insulin resistance, hyperglycemia, and changes in serum and gonadal concentrations of adipokines, like leptin, adiponectin, resistin, and ghrelin have been implicated as causes of male infertility in obese males." (PMID 38203349, 2023). "Less attention has been given to resistin, which is secreted from not only (visceral) adipose tissue but also the placenta and seems to be associated with the development of insulin resistance and obesity." (PMID 36830983, 2023). "In critically ill patients, resistin is associated with sepsis severity, inflammatory factors, and insulin resistance." (PMID 37834432, 2023). "In recent years, interest has grown in some novel adipokine candidates, e.g., chemerin, visfatin, resistin, and apelin, which are strongly associated with obesity and insulin resistance, mainly in humans." (PMID 37889693, 2023). "During pregnancy, elevated levels of resistin and adipokines are generally linked to an increase in insulin resistance." (PMID 37889693, 2023). "So far, many studies have reported that ketone bodies can reduce insulin resistance and serum resistin levels, which is a proven risk factor for atherosclerosis." (PMID 35409148, 2022). "It is worth mentioning that bio-products based on Citrus help in glycemic control, possibly by reducing resistin, an adipocytokine whose increase has been associated with insulin resistance, atherosclerosis, oxidative stress, and inflammation." (PMID 35237168, 2022). "In rodents, positive associations are found between resistin expressed in white adipocytes with BMI and insulin resistance." (PMID 34996484, 2022). "Both leptin and resistin are pro-inflammatory adipokines overproduced during obesity and associated with insulin resistance." (PMID 35327570, 2022). "Increased resistin secretion, produced by adipose tissue in rodents and by immune cells in humans, induces insulin resistance associated with systemic and tissue inflammation." (PMID 36078135, 2022). "In diabetic patients, resistin appears to be linked to insulin resistance and has played a role in upregulating pro-inflammatory cytokines." (PMID 36289594, 2022). "The adipokines leptin and resistin have also emerged as potential causes of insulin resistance, as they interfere with insulin receptor substrate-1 and lead to its degradation." (PMID 35885550, 2022). "For example, increased levels of leptin and resistin are associated with elevated caloric intake and insulin resistance." (PMID 35499991, 2022). "There was a reduction in the expression of resistin, an adipokine associated with adipocyte insulin resistance." (PMID 34086911, 2021). "Due to its pro-inflammatory activity, resistin was linked to the development of insulin resistance and type 2 diabetes, atherosclerosis and cardiovascular diseases." (PMID 33753732, 2021). "Previous studies have shown that resistin has been linked to obesity, diabetes, insulin resistance, DN and NAFLD." (PMID 34603198, 2021). "Previous studies have reported that RETN, an adipokine associated with insulin resistance, is downregulated in the skeletal muscle of rats fed on a high-fat and high-protein diet." (PMID 34564398, 2021). "In humans, however, studies investigating resistin’s association with insulin resistance and T2DM are inconclusive and resistin has stronger implications in atherosclerosis and cardiovascular disease." (PMID 33716966, 2021). "Overall, resistin levels were positively associated with age, hypertension, waist circumference, insulin levels and the degree of insulin resistance (HOMAIR), triglycerides and creatinine levels, and inversely with HDL-C concentrations." (PMID 34496965, 2021). "Bloated fat cells secrete tumor necrosis factor alpha (TNF-α) and resistin, which are mediators of insulin resistance that are closely linked to type 2 diabetes." (PMID 32932138, 2020).
Insulin resistance (continued). "Recently, our group reported on the role of several adipokines (adiponectin, leptin, resistin, and visfatin) in patients with HS and investigated the possible associations with insulin resistance, HS risk, and disease severity." (PMID 32992947, 2020). "Evidence suggests that visceral fat is the largest contributor to circulating resistin levels, supporting the case for an association between resistin and insulin resistance." (PMID 32158768, 2020). "The results of the present study do not clearly indicate that the obese group before weight loss had insulin resistance, but lower resistin gene expression after weight loss suggests that obese animals are more prone to the action of this substance." (PMID 32966299, 2020). "Resistin has been implicated in the insulin resistance observed in normal pregnancy, as the level of resistin increases with gestational age and decreases after delivery." (PMID 32762639, 2020). "Next, increased circulatory levels of the adipokine, RETN, which modulates glucose tolerance and insulin action, have been linked to a higher incidence of insulin resistance and PCOS." (PMID 30975191, 2019). "In rodents, resistin represents a clear pathogenic factor in the severity of insulin resistance (IR)." (PMID 31505789, 2019). "To date, no systematic reviews or meta-analysis has analyzed the association between resistin and insulin resistance in populations; therefore, we analyzed this association in the present study." (PMID 31803062, 2019). "Within the group of down-regulated genes, the Resistin (RETN) gene, it is associated with lipid metabolism, cause insulin resistance and decreased adipocyte differentiation." (PMID 31083386, 2019). "An index based on the relative proportion of adiponectin-to-resistin has been proposed to have diagnostic potential for insulin resistance." (PMID 29785210, 2018). "Resistin is an adipokine that is positively associated with adipose tissue inflammation and insulin resistance." (PMID 29587377, 2018). "Firstly, disturbed regulation of adipokines, including resistin and visfatin, as well as adiponectin, is implicated in the development of insulin resistance and T2DM." (PMID 29744365, 2018). "Individuals with MetS generally present high circulating concentrations of resistin and leptin, inducing leptin resistance and a decrease in adiponectin associated with insulin resistance." (PMID 30400222, 2018). "It was discovered in mice 16 years ago and called “adipose tissue-specific secretory factor”, but the name “resistin” is used due to its association with insulin resistance." (PMID 29584687, 2018). "High serum resistin level, due to its pro-inflammatory properties, was linked to the development of insulin resistance and type 2 diabetes (T2DM), to atherosclerosis and cardiovascular diseases in rodents and in some human studies." (PMID 29213336, 2017). "Animal and human studies have linked production of the adipokine resistin to insulin resistance in the obese, and increased expression has been correlated with increasing central obesity." (PMID 27465935, 2017). "The aim of the study was to determine the role of adiponectin, leptin and resistin in various types of dementia and to investigate their association with inflammatory markers, insulin resistance and abdominal obesity." (PMID 28421328, 2017). "Circulating resistin levels have been positively associated with central obesity as well as insulin resistance in rodents; however, their significance remained controversial in human studies." (PMID 28298189, 2017). "Data on the association of systemic resistin with insulin resistance in patients with liver cirrhosis are inconsistent." (PMID 28661458, 2017). "Lebeche presented an interesting conception about a high level of resistin, as a consequence of obesity, which can be a potential cause of insulin resistance and cardiac dysfunction." (PMID 28396699, 2017).
Insulin resistance (continued). "NDST4 has been found to be associated with levels of circulating resistin, a hormone reported to be associated with insulin resistance, T2D, and cardiovascular disease." (PMID 29079728, 2017). "In an Indian study, plasma resistin levels were also positively associated with waist circumference and insulin resistance." (PMID 28298189, 2017). "Meanwhile, visceral fat is associated with insulin resistance, mediated by resistin secreted from adipocytes producing inflammatory markers, and both visceral fat and insulin resistance were found to be predictors for cardiovascular mortality in ESRD patients." (PMID 28207885, 2017). "On the other hand, cytokines, such as tumor necrosis factor (TNF-α) and resistin, play an important role in cardiovascular risk and insulin resistance." (PMID 27608037, 2016). "In white adipocytes, Hcy induced endoplasmic reticulum stress, unregulated the expression of resistin, and further caused insulin resistance." (PMID 26758372, 2016). "We also examined resistin levels that is associated with increased insulin resistance in adipocytes." (PMID 27055280, 2016). "In contrast to adiponectin, resistin is considered a pro-inflammatory protein with atherogenic effects and is associated with peripheral insulin resistance 30,33." (PMID 28076515, 2016). "Myocardial infarction (MI) was associated with insulin resistance, in which resistin acts as a critical mediator." (PMID 26811539, 2016). "This study assessed associations between serum concentrations of adiponectin/resistin and parameters of insulin resistance in children from 4 different countries." (PMID 25904939, 2015). "The aim of this study was to investigate the relationship between the single nucleotide polymorphism (SNP) -420C > G in the resistin gene with serum resistin levels, insulin resistance, and risk of gestational diabetes (GDM) in Iranian population." (PMID 25945322, 2015). "Although the association between elevated circulating resistin and insulin resistance has been suggested in some studies, other studies fail to detect such an association." (PMID 25945322, 2015). "The aim of our population-based comparison study was to investigate the potential associations between insulin resistance and serum concentrations of adiponectin and resistin, in young and older children from 4 countries: Japan, Thailand Italy, and the USA." (PMID 25904939, 2015). "The decreased expression levels of resistin observed in our study were in line with these previous studies, as SHRs were reported to be predisposed to insulin resistance." (PMID 26517713, 2015). "Murine resistin was initially identified as a hormone secreted by adipocytes that caused insulin resistance, a disorder that can result in type 2 diabetes." (PMID 25568944, 2015). "Coupled with population studies linking resistin levels with increased metabolic risk factors and insulin resistance, resistin is suggested to play a role in the pathophysiology of diabesity through inflammatory contributions." (PMID 26097512, 2015). "The previous study showed that elevated plasma resistin is associated with hepatic insulin resistance induced by 3 weeks' HFD feeding in mice and that treatment with antisense resistin suppressed hepatic glucose production." (PMID 25922835, 2015). "This lack of direct evidence for an association of resistin with T2DM, insulin resistance or metabolic syndrome deterred many investigators from pursuing the role of resistin in T2DM further." (PMID 26097512, 2015). "The aim of our population-based comparison study was to investigate the potential association between insulin resistance and adiponectin and resistin, in young and older children from 4 countries, Japan, Thailand, Italy and the USA." (PMID 25904939, 2015). "It was reported that resistin played a pathogenic role in the development of insulin resistance in humans." (PMID 24526524, 2014).
Insulin resistance (continued). "Leptin, TNF-α, and resistin correlating with body fat mass, has been reported to be associated with insulin resistance and atherosclerosis." (PMID 24684833, 2014). "Adipocyte-derived resistin is linked to insulin resistance in rodent models of depression-like behavior while in humans, the role of resistin is less defined." (PMID 25225489, 2014). "Levels of resistin are found to be increased in periodontitis, and resistin plays an important role in inducing insulin resistance, thus increasing the risk for type II diabetes." (PMID 24692844, 2014). "In view of these findings, leptin and adiponectin are likely to be more important in the pathogenesis of pregnancy-associated insulin resistance as compared to resistin." (PMID 25202741, 2014). "Resistin injection in rodent causes insulin resistance whereas with antibodies against resistin increased the insulin sensitivity in obese mice." (PMID 24695544, 2014). "Recently, days after burn injury resistin levels have been reported to be increased and associated with plasma cortisol concentration and with the level of insulin resistance." (PMID 24099533, 2013). "A number of studies have examined plasma resistin levels or adipose resistin expression, and have found variable associations with insulin resistance." (PMID 23497617, 2013). "Population-based studies have shown that resistin levels are associated with metabolic impairments and insulin resistance but the association between resistin levels and insulin sensitivity has been inconsistent in humans." (PMID 23970879, 2013). "Adipocyte-derived resistin is linked to insulin resistance in rodent models, however, human resistin is released from macrophages and its association with cardiometabolic disease is less defined." (PMID 24109426, 2013). "Elevations in resistin and visfatin are also associated with increased inflammation, insulin resistance, and cardiovascular risk." (PMID 24376307, 2013). "High serum resistin concentrations have been found in obese individuals and have been linked to insulin resistance, hence the trend for decreased resistin levels in METABO is an intriguing finding that requires further investigation in a future study." (PMID 23601452, 2013). "The relation between resistin plasma levels, insulin resistance and risk of impaired glucose metabolism in OSA patients has not been investigated." (PMID 23497617, 2013). "The AR index was also more strongly correlated with the insulin resistance indexes and other risk factors including serum insulin, plasma glucose and whole blood HbA1C levels than adiponectin and resistin levels alone." (PMID 21251282, 2011). "Two independent studies, in which recombinant resistin was administered to rodents, argue that resistin can increase blood glucose levels and cause insulin resistance." (PMID 21760816, 2011). "Hyperglycemia, hyperinsulinemia, and elevated resistin levels in both STAT5-deficient lines suggested hepatic insulin resistance upon STAT5 loss." (PMID 21725989, 2011). "Conversely, resistin has been implicated in impairing insulin sensitivity in rodents, while its role in the development of insulin resistance in humans is still controversial." (PMID 21760816, 2011). "Increased TNFα, leptin, and resistin levels and decreased adiponectin expression in adipose tissues are associated with the development of insulin resistance and vice versa." (PMID 20148112, 2010). "In rodents, resistin is produced exclusively by adipocytes, regulates normal glucose homeostasis, and causes insulin resistance at high circulating levels." (PMID 15578112, 2004). "Adipocyte-derived resistin is a circulating protein implicated in insulin resistance in rodents, but the role of human resistin is uncertain because it is produced largely by macrophages." (PMID 15578112, 2004). "Another possible explanation for insulin resistance in psoriasis could be its association with metabolic syndrome and elevated serum levels of resistin." (PMID 40584532, 2025).
Insulin resistance (continued). "Resistin is another adipokine implicated in the pathophysiology of insulin resistance and is found at elevated levels in individuals with a higher BMI, showing strong positive correlations with leptin and insulin concentrations, thereby reinforcing its involvement in glucose dysregulation." (PMID 41334336, 2025). "While its direct causal role in insulin resistance remains debated in human studies, resistin’s consistent association with endothelial dysfunction, atherosclerosis, and adverse cardiac outcomes highlights its potential as both a biomarker and therapeutic target in cardiometabolic diseases." (PMID 41347124, 2025). "LEPR (leptin receptor) resistin (RETN) is associated with insulin resistance, T2D, CVD, and PCOS." (PMID 39859066, 2025). "Insulin resistance and chronic inflammation have been linked to resistin released by adipocytes." (PMID 40013194, 2025). "As its name suggests, resistin is implicated in insulin resistance development." (PMID 40943107, 2025). "In addition, several rodent studies have demonstrated a causal role of resistin in the development of insulin resistance." (PMID 41405347, 2025). "Elevated resistin levels are associated with insulin resistance; targeting resistin could help manage inflammation and improve insulin function." (PMID 40013194, 2025). "In addition to leptin, adipokines such as resistin, which is linked to inflammation and insulin resistance, also likely to decrease with improvements in adiposity and insulin sensitivity." (PMID 41309556, 2025). "Osteoclasts may contribute to glucose uptake-associated insulin resistance through the secretion of resistin." (PMID 41446289, 2025). "On the other side, resistin has been linked to increased inflammation and insulin resistance." (PMID 40013194, 2025). "We hypothesized that there must be some relationship between the ECS and resistin, given that both systems are linked to the development of inflammation and insulin resistance." (PMID 39050819, 2024). "In addition to BMI, several other factors have been shown to be associated with serum resistin levels, such as insulin resistance." (PMID 38486190, 2024). "In turn, pro-inflammatory cytokines (TNF-α and IL-6) have the ability to induce the expression of resistin, which is directly related to insulin resistance and is associated with the activation of inflammatory processes through a pathway dependent on nuclear factor κB (NF-κB)." (PMID 39201576, 2024). "This association may be mediated, at least in part, by lower insulin resistance, the increased mobilization of EPCs, and the promotion of an anti-inflammatory state (i.e., lower levels of resistin)." (PMID 39339817, 2024). "Taken together, our data suggest that the endocannabinoid–resistin axis might regulate insulin resistance associated with mitochondrial dysfunction." (PMID 39050819, 2024). "Another adipokine, resistin, has been associated with insulin resistance and inflammation, and may also play a role in the development and progression of pulmonary hypertension." (PMID 38893645, 2024). "Insulin resistance has been associated with elevated levels of resistin." (PMID 39765824, 2024). "Although data about resistin are limited in the context of pregnancy, the results underline the relevance of a healthy lifestyle during pregnancy, considering the known associations with the development of insulin resistance." (PMID 36830983, 2023). "Resistin is an adipokin that could be released from epicardial adipose tissue and it has been linked to insulin resistance as well as to inflammatory processes." (PMID 37238961, 2023). "A high level of circulating resistin is the main cause of insulin resistance." (PMID 36839230, 2023). "Interestingly, a prominent pathway, RESISTIN, which is known to increase insulin resistance and susceptibility to diabetes, was found to be activated under both PD and PDDM conditions." (PMID 38082425, 2023).